IGFBP7 (insulin like growth factor binding protein 7)
Diseases named in the same sentence as IGFBP7 in open-access papers (continued):
Sharing a sentence is not in itself a finding about the gene and the disease.
kidney damage (17 papers, 2014 to 2025). "Urinary tissue inhibitor of metalloproteinase-2 (TIMP2) and insulin-like growth factor-binding protein 7 (IGFBP7), both early markers of kidney damage, are closely associated with the G1 cell cycle arrest that occurs during the very early phases of AKI." (PMID 34681750, 2021). "The main causes may be that TIMP-2 and IGFBP7, reflecting the stress status of the kidney, are more relevant to kidney damage." (PMID 28340605, 2017). "Accordingly, the development and validation of novel kidney damage/stress biomarkers such as (TIMP-2) × (IGFBP7) has been driven forward in recent years." (PMID 39021823, 2024). "In general, a combination of the biomarkers (urinary TIMP-2 and IGFBP7) for the early detection of perioperative kidney damage and accelerated intervention schemes seems to be the basis for AKI prophylaxis and treatment in surgical settings." (PMID 36614838, 2022). "It should be noted that the available data on the origin and source in renal compartment are preliminary and IGFBP-7 remains only a candidate molecule in the setting of nephropathy outside of acute care." (PMID 34946293, 2021). "uNGAL is a marker of tubular injury and its concentration rises immediately after AKI, while the proteins TIMP-2 and IGFBP7 jointly participate in the G1 phase cell cycle arrest processes and their tubular expression and urinary excretion increase in response to kidney damage." (PMID 40025594, 2025). "Urinary TIMP-2 and IGFBP7 concentrations are considered to be markers of kidney damage." (PMID 32487237, 2020). "Further, in contrast to recently developed damage biomarkers such as TIMP2•IGFBP7, suPAR’s direct pathophysiological involvement and long-lasting kinetics provide robust, longitudinal information on the activity of kidney tissue inflammation, kidney damage, and prognosis in SI-AKI." (PMID 37036003, 2023). "Recent studies reported on the discovery and validation of two urinary G1 cell cycle arrest biomarkers for early diagnosis of kidney damage: tissue inhibitor of metalloproteinase-2 (TIMP-2) and insulin-like growth factor-binding protein 7 (IGFBP7)." (PMID 26606754, 2015). "The findings of this study suggest that using [TIMP2]*[IGFBP7] at 12 h could lead to the early detection of severe AKI, prompting additional clinical action to hinder further kidney damage." (PMID 36673127, 2023). "Other biomarkers of kidney damage, such as [TIMP2]*[IGFBP7] or NGAL may be able to identify and quantify kidney stress or damage early on in the course of AKI, but are likely of limited value for peri-RRT assessment of kidney recovery." (PMID 36316692, 2022). "The use of TIMP2 × IGFBP7 biomarkers at admission could, therefore, be helpful in the trauma setting, where implementation of an AKI care bundle to prevent or interrupt the mitigation of kidney damage is possible." (PMID 36292170, 2022).
colon cancer (15 papers, 2010 to 2024). "In addition, IGFBP7, a tumor associated stroma markers with growth-promoting effects in colon cancer through a paracrine tumor -stroma interaction, was highly expressed in the stromal compartment." (PMID 38473208, 2024). "For instance, IGFBP7 promoted colon cancer development through paracrine tumour‐stroma interactions." (PMID 39351597, 2024). "In turn, IGFBP7-expressing CAFs can induce colony formation in colon cancer cells suggesting a paracrine tumor–stroma interaction." (PMID 37296997, 2023). "In liver cancer, IGFBP7 induces anti-tumor effects by binding to the IGF1 receptor (IGF1R) to inhibit IGF signaling; in colon cancer, IGFBP7 down-regulates EMT to promote liver metastasis." (PMID 37568781, 2023). "Depletion of neutrophils in mice reduced protein levels of both pSMAD3 and IGFBP7 within colon tumors, suggesting that tumor‐infiltrating neutrophils activate TGFβ signaling in colon adenomas throughout their formation." (PMID 31793740, 2020). "IGFBP7 can induce colony formation in colon cancer cells co-cultured with IGFBP7-expressing CAFs by a paracrine tumor-stroma interaction." (PMID 25919140, 2015). "Recent studies have further indicated that IGFBP7 expression is repressed by methylation –dependent mechanisms in colon cancers while its paralog KAZALD1 is often methylated and silenced in MPM." (PMID 24690739, 2014). "We have identified six candidate proteins whose expression were downregulated by reintroduction of IGFBP7 in the colon cancer RKO cells using a proteomics approach." (PMID 20433702, 2010). "Here we describe a proteomics study of two human colon cancer cell lines differing in the expression of IGFBP7, which is an important tumor suppressor gene well defined by our previous studies." (PMID 20433702, 2010). "A DNA methylation inhibitor attenuated migration ability through induction of IGFBP7 in colon cancer cell lines, and IGFBP7 could inhibit cell growth of breast tumor cells." (PMID 30613364, 2018). "Downregulation of FOXD3 levels by promoter methylation in colon cancer might provide a favorable setting for either acquisition of a BRAF mutation or proliferation by RAS-RAF-MEK over-activation, similar to IGFBP7." (PMID 23324568, 2013). "A senescence-like phenotype was induced by IGFBP7 in these colon cancer cells." (PMID 20433702, 2010). "Downregulation of HSP60 may participate in, at least in part, the growth inhibiting role of IGFBP7 on colon cancer cells." (PMID 20433702, 2010). "Furthermore, IGFBP7 expression in cancer stromal cells supported the growth of colon cancer cells." (PMID 25887188, 2015). "By IHC and real-time quantitative reverse-transcriptase PCR (qRT-PCR), they found that substantial variations in IGFBP7 were identified in stage III and IV colon cancer compared to adjacent nontumour tissue." (PMID 37660019, 2023).
Obesity (15 papers, 2015 to 2025). Accumulation of substantial excess body fat. "IGFBP7, a key regulator of cell growth, is associated with cellular senescence, tissue aging, and obesity, and its high concentrations have been linked to diastolic dysfunction." (PMID 41444673, 2025). "This is possibly associated with the fact that obesity is an agent related to senescence, and IGFBP7 is secreted by senescent cells." (PMID 36658131, 2023). "IGFBP-7 is a biomarker linked to metabolic disorders like type 2 diabetes and obesity." (PMID 38255264, 2024). "Together with the evidences with the associations of IGFBP7 with metabolic components, These findings indicated that IGFBP7 independently associated with MetS and its biological effects might be mediated by obesity, LDL and HDL etc." (PMID 25984973, 2015). "The identification and exploration of biomarkers such as GLP-1, GIP, MCP-1, and IGFBP-7 have provided valuable insights into the complex pathophysiology of metabolic disorders, including type 2 diabetes and obesity." (PMID 38255264, 2024). "Obesity is considered to promote PI3K/Akt signaling through mechanisms involving increased levels of insulin and leptin, and possible relationships between obesity, IGFBP7 expression, and ganitumab sensitivity deserve further study." (PMID 39362991, 2024). "There is also a relationship between IGFBP-7 concentration and obesity." (PMID 35813634, 2022). "Together with these evidences, these findings indicated that IGFBP7 was an independent predictor for MetS and its effect on IR might be mediated by obesity." (PMID 25984973, 2015). "Biomarkers identified as potential factors associated with the development of metabolic disorders such as type 2 diabetes and obesity, namely GLP-1, GIP, MCP-1, and IGFBP-7, have been the subject of extensive scientific research." (PMID 38255264, 2024). "A comparison of the obesity and control groups revealed differences in the expression of IGF2, IGFBP1, and IGFBP7 genes." (PMID 34371941, 2021). "Age, obesity, and previous cardiac disease were significantly associated with incidence of AKI, whereas the shock index, ISS, and TIMP2 × IGFBP7 values were not." (PMID 36292170, 2022).
prostate carcinoma (15 papers, 2010 to 2024). A carcinoma that arises from epithelial cells of the prostate gland. "IGFBP7 merits further study as a treatment predictive biomarker in other cancer types such as colon, ovarian and prostate cancer, as well as sarcomas, where IGF-1R targeting agents have been investigated." (PMID 39362991, 2024). "Aberrant promoter hypermethylation of IGFBP7 and consequential gene silencing were found in prostate cancer cell lines." (PMID 36743211, 2023). "IGFBP7, a member of the insulin growth factor binding protein family, is involved in a variety of cancers including prostate cancer." (PMID 36743211, 2023). "Several previous studies have detailed that IGFBP7 gene expression is significantly diminished in prostate carcinoma based on RT-PCR, northern blot, and in situ hybridization (ISH)." (PMID 32500027, 2020). "Other downregulated genes, including SELENBP1 and IGFBP7, seen in CAFs have previously been reported to be tumor suppressors with proapoptotic and antiproliferative effects on prostate cancer cells." (PMID 28831065, 2017). "In-vitro studies demonstrated that IGFBP7 induced the apoptosis of many cancer cells, e.g., breast and prostate cancer cells, and plays a potential tumor suppressor role against colorectal carcinogenesis." (PMID 20158915, 2010). "Recent data also demonstrated that a prostatic carcinoma cell line stably transfected with IGFBP7 cDNA showed poor tumorigenicity both in vitro and in vivo." (PMID 20158915, 2010). "The results also suggest that the CpG methylation of IGFBP7 may be a unique biomarker of prostate cancer and pre-invasive neoplasms." (PMID 32500027, 2020). "Also, prostatic carcinoma cells were stably transfected with IGFBP7 cDNA and showed poor tumorigenicity." (PMID 20158915, 2010). "More recently, an assay that evaluates the methylation of GSTP1, SFRP2, IGFBP3, IGFBP7, APC and PTGS2 genes to specifically identify individuals with a severe probability of developing prostate cancer has been proposed." (PMID 37511475, 2023).
COVID-19 (13 papers, 2020 to 2025). A disease caused by infection with severe acute respiratory syndrome coronavirus 2. "A clinical trial has been established to study whether TIMP-2 and IGFBP7 could identify patients with COVID-19 at risk of developing AKI early (NCT04393428), and the findings of this investigation will be made public in the future." (PMID 35930243, 2022). "For instance, urine [TIMP-2]x[IGFBP7] results have been shown to predict moderate to severe AKI in patients with severe COVID-19 and acute respiratory distress syndrome." (PMID 40055234, 2025). "The efficacy of urine TIMP-2 and IGFBP-7 to predict AKI in patients with COVID-19 has been examined." (PMID 39001241, 2024). "While research on the applications of TIMP2 and IGFBP7 is promising in some settings, it is scarce in the context of COVID-19, with few and contradictory results." (PMID 36673127, 2023). "The objective of this study was to assess the utility of [TIMP2]*[IGFBP7] biomarkers as predictors of severe AKI in a population of critically ill COVID-19 patients." (PMID 36673127, 2023). "A small study reported that patients with COVID-19-associated AKI and high levels of [TIMP-2] × [IGFBP7] were more likely to progress to renal replacement therapy than those with AKI but with low [TIMP-2] × [IGFBP7]." (PMID 35204776, 2022). "Plasma analysis confirmed distinct fibrosis biomarkers (TSP2, GDF15, IGFBP7, Pro-C3) that predicted the fatal trajectory in COVID-19." (PMID 36206625, 2022). "In view of the need to identify the early signs of kidney involvement, this study was aimed at exploring the role of the urinary biomarkers NGAL, TIMP-2, and IGFBP7 for the early detection of AKI in critically ill patients with COVID-19." (PMID 35204776, 2022). "IGFBP7 mRNA levels were unaltered in patients with bacterial sepsis but were low in renal tissue from COVID-19 patients (fold change 0.46, p = 0.014)." (PMID 34112226, 2021). "While urine alkalinization is feasible and can increase urine pH, we could not demonstrate differences in AKI rates or changes in urine [TIMP-2]x[IGFBP7] concentrations in critically ill COVID-19 patients." (PMID 40055234, 2025). "Although it may serve as an early indicator of acute kidney stress, few studies have investigated the value and clinical application of [TIMP-2] • [IGFBP7] in COVID-19." (PMID 35930243, 2022). "We hypothesize that plasma markers (e.g. (TSP2, GDF15, IGFBP7, Pro-C3) could detect the of early fibrotic changes in COVID-19." (PMID 36206625, 2022). "In critically ill patients with COVID-19, the combination of [TIMP-2] × [IGFBP-7] and clinical data proved helpful in identifying subclinical AKI." (PMID 39001241, 2024). "New cell-cycle arrest biomarkers [TIMP2]*[IGFBP7] have been proposed for early detection of AKI, but their role in critically ill COVID-19 patients is poorly understood." (PMID 36673127, 2023). "Furthermore, genetic susceptibility for IPF and COVID-19 seem to be similar, as confirmed by the fibrotic plasma biomarkers such as thrombospondin 2 (TSP2), glial-derived factor 15 (GDF15), insulin-like growth factor binding protein 7 (IGFBP7), and procollagen type III (PROC3)." (PMID 36966238, 2023). "In critical COVID-19 patients, the urinary biomarker [TIMP2]*[IGFBP7] were generally elevated, and were higher in severe AKI when sampled at 12 h after ICU admission, but not at other timepoints." (PMID 36673127, 2023). "More studies should be carried out to investigate the effect of [TIMP-2] • [IGFBP7] in predicting AKI and the progress of the disease and determine its clinical usage in the phenotyping of clinical AKI in patients with COVID-19." (PMID 35930243, 2022). "ATI as the primary lesion of COVID-19-associated AKI is also consistent with a urinary-biomarker study demonstrating that COVID-19 patients with stage 2 and 3 AKI have elevated levels of urinary [TIMP-2] • [IGFBP7] and tubular (α-1-microglobulin) proteinuria." (PMID 35216358, 2022).
COVID-19 (continued). "The combination of [TIMP-2] × [IGFBP7] together with clinical information, were useful for the identification of subclinical AKI in critically ill COVID-19 patients." (PMID 35204776, 2022). "Patients with COVID-19 AKI and high levels of tissue inhibitor of metalloproteinases-2 and insulin-like growth factor-binding protein-7 [TIMP-2] × [IGFBP-7] were more likely to progress to RRT than patients with AKI but with low [TIMP-2] × [IGFBP-7]64." (PMID 33060844, 2020). "Kidney injury biomarkers, such as functional biomarkers (CysC), damage biomarkers (KIM-1, L-FABP, IL-18, suPAR, and NGAL), and stress biomarkers (TIMP-2 and IGFBP7), appear to be efficient in detecting AKI as well as disease progression in patients with COVID-19." (PMID 35930243, 2022). "Up-regulation of NGAL and [TIMP-2] × [IGFBP7] was already significant, indicating that these kidney stress biomarkers may be useful for the diagnosis of subclinical AKI in patients with COVID-19." (PMID 36499745, 2022).
type 2 diabetes (12 papers, 2008 to 2025). "Here we have, for the first time, characterized IGFBP7 in human pancreatic islets with focus on expression levels in type 2 diabetes and potential function of this insulin binding protein." (PMID 39280605, 2024). "To assess if manipulation of endogenous IGFBP7 affects β-cell physiology, we knocked down IGFBP7 using siRNA in both EndoC-βH1 cells and in islets from three human donors with type 2 diabetes/IGT." (PMID 39280605, 2024). "In order to investigate IGFBP7 expression in islet cells at the protein level, we immunostained pancreatic sections from ND donors and type 2 diabetes donors for IGBFP7, glucagon, and insulin (for donor information)." (PMID 39280605, 2024). "IGFBP7 is present in human serum/plasma in the low nanomolar range and is elevated in the serum of newly diagnosed men with type 2 diabetes." (PMID 39280605, 2024). "We also explored how manipulation of IGFBP7 levels impact the function of type 2 diabetes human donor islets." (PMID 39280605, 2024). "In α-cells, IGFBP7 expression is upregulated by ∼30% in type 2 diabetes donors compared to control whereas the levels in β-cells remain unchanged." (PMID 39280605, 2024). "With this approach, we confirmed that the IGFBP7 intensity was increased by ∼20% in α-cells from type 2 diabetes donors compared to control." (PMID 39280605, 2024). "We present evidence that IGFBP7 is a negative regulator of insulin secretion and is upregulated in type 2 diabetes." (PMID 39280605, 2024). "Conversely, IGFBP-7 exhibits a high binding affinity for insulin but low for IGFs, which makes serum IGFBP-7 levels an interesting target for studying type II diabetes mellitus." (PMID 36076984, 2022). "IGFBP-7 DNA methylation levels and IGFBP-7 serum concentrations are increased in newly diagnosed type 2 diabetic patients." (PMID 30392760, 2019). "We found that circulating levels of IGFBP7 are enhanced in patients with endometriosis and type II diabetes." (PMID 19019211, 2008). "Patients with endometriosis and those with type II diabetes mellitus undergoing hemodialysis had significantly higher serum concentrations of IGFBP7 than the relevant control subjects." (PMID 19019211, 2008). "Lastly, we examined serum IGFBP7 levels in patients undergoing hemodialysis, many of whom had type II diabetes mellitus." (PMID 19019211, 2008). "Finally, we show that reduction of islet IGFBP7 in type 2 diabetes results in improved insulin secretion." (PMID 39280605, 2024). "Also, β-cells exhibited a more marginal but still significant increase in IGFBP7 in type 2 diabetes donors." (PMID 39280605, 2024). "IGFBP7 gene expression was overall elevated in islets from donors with type 2 diabetes." (PMID 39280605, 2024). "Taken together, our data suggest that IGFBP7 is differentially expressed in islets in type 2 diabetes and that IGFBP7 may be regulated by RUNX1." (PMID 39280605, 2024). "However, nothing is known about the effects of IGFBP7 on insulin secretion in type 2 diabetes, or if IGFBP7 could be a therapeutic target to improve insulin secretion in clinical type 2 diabetes." (PMID 39280605, 2024). "Prior research has indicated that both IGFBP7 and IGFBP5 have significant roles in the progression of type 2 diabetes and its related complications." (PMID 40444232, 2025). "In addition to IGFBP7 we also found IGFBP2 and 6 to be upregulated in type 2 diabetes." (PMID 39280605, 2024).
metabolic syndrome (11 papers, 2015 to 2025). A cluster of metabolic risk factors for CARDIOVASCULAR DISEASES and TYPE 2 DIABETES MELLITUS. "IGFBP-7 has been evidenced as a serum biomarker for diastolic dysfunction associated with vascular remodelling and cardiac hypertrophy and fibrosis, in the metabolic syndrome." (PMID 28231848, 2017). "Therefore, ImpL2/IGFBP7 may not only represent an ancient hormone that promotes fat storage in the adipose tissue but also a suitable drug target for the treatment of metabolic syndrome in humans." (PMID 39711529, 2024). "In the overall study populations, patients with metabolic syndrome showed significant increase in the IGFBP-7/IGF-1 ratio compared to patients without metabolic syndrome (0.53 [0.41-0.74] vs. 0.47 [0.36-0.59], respectively, p =0.002)." (PMID 27769173, 2016).